AUTS2 (activator of transcription and developmental regulator AUTS2)
Diseases named in the same sentence as AUTS2 in open-access papers (continued):
Sharing a sentence is not in itself a finding about the gene and the disease.
Intellectual disability (38 papers, 2010 to 2025). "Given the association of AUTS2 in neurological disorders including autism spectrum disorder, intellectual disability and developmental delay, this finding was clinically significant." (PMID 39653745, 2025). "AUTS2 has subsequently been associated with a diversity of diseases and phenotypes, including intellectual disability, microcephaly, short stature, and developmental delay now known as the AUTS2 syndrome." (PMID 40346605, 2025). "Mutations in the Auts2 gene cause developmental delay, intellectual disability, microcephaly, and short stature." (PMID 36803626, 2023). "Haploinsufficiency of AUTS2 has been associated with a syndromic form of neurodevelopmental delay characterized by intellectual disability, autistic features, and microcephaly, also known as AUTS2 syndrome." (PMID 34573342, 2021). "Pathogenic variants of the AUTS2 (Autism Susceptibility candidate 2) gene predispose to intellectual disability, autism spectrum disorder, attention deficit hyperactivity disorder, facial dysmorphism and short stature." (PMID 34273950, 2021). "A rare mutation was detected in AUTS2 in which deletions are inherited in an autosomal dominant manner and are associated with neurological symptoms including intellectual disability and developmental delay." (PMID 29458409, 2018). "Following the report of this finding, many studies have found structural variants that disrupt the AUTS2 region and are related to intellectual disabilities and developmental delays." (PMID 25347278, 2014). "AUTS2 is mutated or translocated in autistic patients and individuals with intellectual disabilities, phenotypes shared by patients with Williams-Beuren region duplication syndrome." (PMID 24265791, 2013). "AUTS2 (42 UCEs) has been implicated in neurodevelopment, with several brain-specific enhancers, and is associated with numerous neurological disorders, including autism spectrum disorders, intellectual disability, and developmental delay." (PMID 39058500, 2024). "Mutations in the AUTS2 gene have also been identified in patients with mental retardation." (PMID 24690944, 2014). "Autism susceptibility candidate 2 (AUTS2) (also termed “activator of transcription and developmental regulator”) has been identified in human genetic studies as a risk gene for numerous types of psychiatric illnesses, including ASDs, intellectual disabilities (IDs), and schizophrenia." (PMID 33305180, 2020). "Patient 35 presented with a deletion on 7q11.21-11.22, including the AUTS2 gene, which overlaps with Mental Retardation, Autosomal Dominant 26 (MRD26, OMIM 615834)." (PMID 40589517, 2025). "Whereas AUTS2 and SOX5 have been linked to predisposition to neurological conditions such as autism spectrum disorder, intellectual disability, and neurodevelopmental disorder." (PMID 39535534, 2024). "AUTS2 is associated with multiple mental disorders, including ASD, intellectual disability and schizophrenia." (PMID 33242228, 2021). "In human patients, AUTS2 mutations are associated with a variety of psychiatric diseases, such as ASD, schizophrenia, depression, intellectual disabilities, and language disability." (PMID 32498016, 2020). "Autism Susceptibility Candidate 2 (AUTS2) was originally identified as the gene disrupted by reciprocal translocation in human twins with Autism spectrum disorder (ASD), intellectual disability (ID), and epilepsy." (PMID 31554716, 2019). "AUTS2 was originally discovered as the gene disrupted by a translocation in human twins with Autism spectrum disorder, intellectual disability, and epilepsy." (PMID 31554716, 2019). "Mutations in the Autism susceptibility candidate 2 gene (AUTS2) have been associated with a broad range of psychiatric illnesses including autism spectrum disorders, intellectual disability and schizophrenia." (PMID 26717414, 2015).
Intellectual disability (continued). "For example, constitutional intragenic deletions within AUTS2, IMMP2L, and NRXN1 have been associated with autism spectrum disorder, intellectual disability, and psychiatric disorders." (PMID 25373142, 2015). "AUTS2 is related to neurodevelopment, autism spectrum disorders and intellectual disability." (PMID 39020437, 2024). "Such a 450-gene panel for intellectual deficiency showed a heterozygous duplication of a single nucleotide, Chr7(GRCh37): g.70236569dup, ENST00000342771.4: c.1769dup in exon 11 of AUTS2, leading to a frame shift expected to produce a premature stop codon, p.(Met593Tyrfs*85)." (PMID 34273950, 2021). "AUTS2 codes for a chromatin-remodeling protein that functions as a component of the polycomb repressive complex 1 (PRC1); loss of function mutations can lead to ASD, SZ and intellectual disabilities." (PMID 28321286, 2017). "AUTS2 is an important gene for neurodevelopment in vertebrates that has received long-term attention due to its link with a diversity of neurodevelopmental disorder features including intellectual disability, microcephaly, short stature, and developmental delay, known as the AUTS2 syndrome." (PMID 40346605, 2025). "Accordingly, AUTS2 was involved in many types of neurological diseases, including autism spectrum disorders (ASD), intellectual disability and developmental delay." (PMID 33242228, 2021). "Of particular interest to us is the fact that AUTS2 is a candidate for several neurodevelopmental disorders, including ASD, intellectual disability, and developmental delay (see Oksenberg and Ahituv, 2013, for discussion)." (PMID 26136701, 2015).
microcephaly (26 papers, 2013 to 2025). A congenital or acquired developmental disorder in which the circumference of the head is smaller than normal for the person's age and sex. "Here, we analyze mice mutated for the transcriptional regulator AUTS2, which recapitulate microcephaly." (PMID 39815005, 2025). "Autism susceptibility candidate 2 (AUTS2)-COs confirmed the previous findings on cell cycle disruption in microcephaly, showing decreased NPC proliferation and increased asymmetrical divisions, leading to premature neuron generation and cell disorganization." (PMID 39062993, 2024). "In auts2a morphants, AUTS2 deficiency resulted in microcephaly, decreased neurogenesis, and other growth defects." (PMID 35431798, 2022). "The knockout or loss-of-function mutation of Auts2 causes microcephaly, neuron reduction, increased excitatory synapses, and ASD-like behaviors." (PMID 34947998, 2021). "In humans, individuals with AUTS2 mutations exhibit a wide range of pathological features, including microcephaly, corpus callosum hypoplasia, and psychiatric illnesses." (PMID 35011572, 2021). "Human genetic studies have previously reported that individuals with mutations in AUTS2 locus exhibited common features including ID, developmental delay, microcephaly, and epilepsy but distinct psychiatric disorders such as ASDs, ADHD, and schizophrenia." (PMID 32498016, 2020). "Previous clinical studies reported that some individuals with AUTS2 mutations display microcephaly, motor delay, and speech delay." (PMID 33305180, 2020). "These common pathological features including ID, microcephaly and craniofacial abnormalities, except for the autistic features among the individuals with AUTS2 mutations, have been recently termed “AUTS2 syndrome”." (PMID 28505103, 2017). "Although microcephaly may be caused by a decrease in the number of neurons, the mechanism by which microcephaly is caused due to impaired AUTS2 function remains unclear." (PMID 39815005, 2025). "Disruptions in the AUTS2 gene are associated with microcephaly in human patients." (PMID 35431798, 2022). "Additionally, patients with AUTS2 mutations often display other pathological conditions including developmental delay, microcephaly, short stature, and craniofacial dysmorphisms; a series of such symptoms are termed “AUTS2 syndrome”." (PMID 35011572, 2021). "The function of FBRSL1 is largely unknown, but pathogenic variants in the FBRSL1 paralog Autism Susceptibility Candidate 2 (AUTS2) are causative for an intellectual disability syndrome with microcephaly (AUTS2 syndrome)." (PMID 34805182, 2021). "This study not only leads to a better understanding of the pathogenesis of microcephaly in AUTS2 syndrome and the molecular function of AUTS2, but also sheds light on the evolution of the mammalian brain." (PMID 39815005, 2025). "In another study, Beunders and colleagues reported on 24 individuals with exonic deletions of AUTS2 and manifesting variable set of features, including intellectual disability, autism, microcephaly, short stature, and facial dysmorphism." (PMID 34099044, 2021). "Auts2 knockdown in zebrafish leads to morphants recapitulating part of the human phenotype including microcephaly and smaller lower-jaw size." (PMID 32424618, 2020). "This microcephaly phenotype is also observed in mice and human patients with AUTS2 disruptions suggesting a critical role for AUTS2 in neurodevelopment and growth." (PMID 26483618, 2015). "It has been reported that individuals with heterozygotic disruptions of the human AUTS2 occasionally present with brain malformations including microcephaly and corpus callosum hypoplasia." (PMID 26717414, 2015). "Although the precise function of AUTS2 has long remained unclear, the knockdown of Auts2 in zebrafish by morpholino exhibited microcephaly with a decrease of neurons in the developing brain, suggesting that AUTS2 is required for proper neural development." (PMID 26717414, 2015).
microcephaly (continued). "It has been reported that a subset of patients harboring deletions within exonic regions of AUTS2 present with a short stature, facial dysmorphism, and microcephaly." (PMID 26483618, 2015). "In zebrafish, reductions of AUTS2 by morpholinos knockdown results in microcephaly, reduced mobility and decreases in the number of neurons." (PMID 26483618, 2015). "Understanding the etiology of microcephaly in AUTS2 and other neurodevelopmental disorders has been limited by the primary use of mouse models which do not adequately recapitulate the manner and severity in which microcephaly arises." (PMID 35431798, 2022). "The hypothesis that the C-terminal part of the protein mediates major AUTS2 functions was further supported by Auts2a knockdown experiments in zebrafish, in which expression of the C-terminal isoform rescued the microcephaly phenotype." (PMID 35431798, 2022). "Furthermore, they showed that Morpholino-mediated knockdown of zebrafish Auts2 resulted in microcephaly and reduced lower jaw size, comparable to defects seen in patients with an AUTS2 disruption." (PMID 34805182, 2021). "Additional structural variants of AUTS2, some of which are intronic, have also been shown to be associated with attention deficit hyperactivity disorder (ADHD) epilepsy, dyslexia, language delay, visual impairment, microcephaly and other conditions." (PMID 25347278, 2014). "Additional structural variants in AUTS2, some of which are only intronic, were also shown to be associated with attention deficit hyperactivity disorder (ADHD), epilepsy, dyslexia, motor delay, language delay, visual impairment, microcephaly and others." (PMID 23349641, 2013). "Since microcephaly-like phenotypes have not been reproduced in in vivo models of animals with neocortex, the mechanism by which microcephaly is caused by loss of AUTS2 remains unclear." (PMID 39815005, 2025). "Mouse models for Auts2 deficiency do not demonstrate microcephaly." (PMID 35431798, 2022). "Furthermore, the full-length or the 3′ end short transcripts of human AUTS2 were found to rescue several abnormalities including the microcephaly and dysmorphisms in the morphant fish, suggesting that the C-terminal region of AUTS2 contains the crucial elements for neurodevelopment." (PMID 28505103, 2017). "However, the specific hippocampal and cerebellar pathologies we identified in 16GsoT/T mice have not been previously associated with any Auts2 mouse mutations and other than generalized microcephaly, specific brain pathologies have not been described for human AUTS2 patients to date." (PMID 31554716, 2019). "This study reveals that murine AUTS2 promotes H3K27 trimethylation to suppress gene transcription and division of intermediate progenitor cells (IPCs), thereby contributing to the development of microcephaly." (PMID 39815005, 2025). "As mentioned, other than microcephaly, brain pathology has not been reported for human AUTS2 patients." (PMID 31554716, 2019).
autism spectrum disorder (23 papers, 2014 to 2025). A spectrum of developmental disorders that includes autism, and Asperger syndrome. "The autism susceptibility candidate 2 (AUTS2) gene at 7q11.2 was first identified and found disrupted because of a balanced translocation in a pair of monozygotic twins with autism spectrum disorder (ASD)." (PMID 39897131, 2025). "AUTS2 mutation is linked to autism spectrum disorders, epilepsy, cerebral palsy, facial dimorphism, developmental delays, mental retardation, and schizophrenia, among other disorders." (PMID 36895015, 2023). "Auts2 has been linked to many psychiatric disorders, including autism spectrum disorders and schizophrenia, and animal studies demonstrated that AUTS2 regulates emotional control, cognitive memory and social communication in mice." (PMID 35338311, 2022). "The genes Auts2 and Shank3 are associated with autism spectrum disorders and other neurological diseases, and in this study both of the genes exhibited an alteration in methylation pattern in the gene body." (PMID 24484737, 2014). "Mutations in AUTS2 are strongly associated with autism spectrum disorders." (PMID 39534499, 2024). "Thus, AUTS2 may be used as a biomarker for autism spectrum disorder risk." (PMID 39584967, 2024). "In recent years, the role of the AUTS2 gene in developing autism spectrum disorders has been extensively studied in humans." (PMID 34327051, 2021).
epilepsy (23 papers, 2010 to 2024). A brain disorder characterized by episodes of abnormally increased neuronal discharge resulting in transient episodes of sensory or motor neurological dysfunction, or psychic dysfunction. "AUTS2 is a crucial gene associated with neuropsychological disorders such as epilepsy though its role in macrophage function is yet to be defined." (PMID 38480935, 2024). "Many studies have previously demonstrated that AUTS2 was implicated as a promising candidate for multiple neurocognitive defects as well as developmental delay and epilepsy." (PMID 26717414, 2015). "Thus, investigation of spontaneous electrical activities and potential alterations in neural network properties in AUTS2 deficient COs would lead to greater understanding of mechanisms underlying epilepsy in AUTS2 syndrome." (PMID 35431798, 2022). "However, the neurodevelopmental impact of altered differentiation on synaptic physiology and how loss of AUTS2 leads to epilepsy in AUTS2 syndrome remains unclear." (PMID 35431798, 2022). "In line with this, the AUTS2 gene has been associated with ASD and other disorders, such as attention deficit hyperactivity disorder, epilepsy, and dyslexia." (PMID 36835010, 2023). "AUTS2 is a well-known risk gene for autism spectrum (ASD) but also for other neurodevelopmental disorders, including epilepsy." (PMID 36575526, 2022). "DLG2 belongs to the gene motif “BGNADP”, which is a network associated with ID and epilepsy, including also BTD, GALNT10, NMUR2, AUTS2, and PTPRD." (PMID 35627244, 2022). "Two genes were altered in two patients each: AUTS2 deletions were identified in one proband with juvenile myoclonic epilepsy (JME) and one proband with unclassified non-lesional epilepsy with features of atypical benign partial epilepsy (ABPE)." (PMID 20502679, 2010).
developmental delay (21 papers, 2014 to 2025). "To date, there are only four patients reported in HGMD with a pathogenic intragenic duplication of AUTS2, three involving exon 5, and all with developmental delay or ASD." (PMID 34573342, 2021). "We report a patient with developmental delay due to germline AUTS2 mutation who developed a low-grade astrocytoma." (PMID 29445462, 2017). "In this study, we describe the phenotype of five new patients with AUTS2 pathogenic variants, three of them harboring loss-of-function sequence variants, characterized by developmental delay, autistic features, and attention deficit hyperactivity disorder (ADHD)." (PMID 34573342, 2021). "Both copy number variation (CNV) duplications and deletions of AUTS2 were found in patients with developmental delay and ASD." (PMID 34947998, 2021). "Auts2 knock-out mice also showed a general developmental delay, including lower body weight and impaired motor skills." (PMID 33967843, 2021). "Auts2 cKO mutants were viable but had a significant reduction in body weight or exhibited developmental delays." (PMID 33305180, 2020). "The Auts2 KO mouse model also results in reduction in size and these mice also display developmental delays, motor deficits, and altered communications as assayed by pup ultrasonic vocalizations (USVs)." (PMID 26483618, 2015). "Notably, 80~100% patients with Auts2 disruption were diagnosed with ID or developmental delay, and ~40% patients had ASD." (PMID 33967843, 2021).